EGFR (epidermal growth factor receptor)
Diseases named in the same sentence as EGFR in open-access papers (continued):
Sharing a sentence is not in itself a finding about the gene and the disease.
cancer (continued). "Although there are EGFR inhibitors targeting the orthosteric binding site of the kinase domain, proteins found in cancer cells often have amino acid substitutions making it insensitive to such inhibitors." (PMID 33110179, 2020). "EGFR transactivation in cancer cells can confer properties, such as growth, survival, and angiogenesis to cancer cells." (PMID 32535812, 2020). "In turn, the RTK-like orphan receptor 1-linked endocytosis complex can activate downstream signaling, such as serine/threonine protein kinase B, of other RTKs, including EGFR in cancer cells." (PMID 32461676, 2020). "Cetuximab targets and inhibits signals from epidermal growth factor receptor (EGFR) expressed in some cancers, inducing cell arrest and apoptosis, and bevacizumab blocks the action of vascular endothelial growth factor (VEGF), thereby inhibiting angiogenesis." (PMID 33297561, 2020). "So far, great effort has been directed toward developing anticancer agents with the capacity to interfere with EGFR activity, based on the theory that EGFR signaling is important for the progression of diverse cancers." (PMID 32846937, 2020). "The EGFR pathway when blocked has been reported to have an effect on the signalling pathways and can lead the cancer cells towards the apoptosis stage." (PMID 32104177, 2020). "Erlotinib is a reversible and highly specific EGFR tyrosine kinase inhibitor that is orally administrated in a variety of cancers." (PMID 32660222, 2020). "While active IGF-IR can compensate EGFR inhibition, activation of the EGFR pathway also contributes to anti-IGF-IR drugs resistance in cancer." (PMID 32493414, 2020). "EGFR plays an essential role in the tumorigenesis of a variety of cancers including RCC, where it is commonly overexpressed." (PMID 32413049, 2020). "Cetuximab is an antibody that blocks EGFR signaling and stimulates an immune response against cancer cells." (PMID 33065994, 2020). "In recent years, target therapy using monoclonal antibodies and chemical tyrosine kinase inhibitors have shown high response rates in the treatment of EGFR overexpressing cancers." (PMID 32042390, 2020). "The fabricated aptasensor was demonstrated for the analysis of EGFR and living cancer cells, with the advantages of good anti-interferences ability, stability, and reproducibility." (PMID 33330394, 2020). "Therapeutic mAbs specific to receptor tyrosine kinases (RTK), such as human epidermal growth factor receptor (EGFR) or human epidermal growth factor receptor type 2 (HER2) have been used for targeted treatment of different types of cancers since 90s." (PMID 32577943, 2020). "These EGFR monoclonal antibodies can have different anti-cancer characteristics depending on their Fv and Fc regions." (PMID 32793499, 2020). "Given the frequency of its aberrations, EGFR represents an appealing target for inhibition in this type of cancer." (PMID 32672423, 2020). "Upregulation of MUC1 promoted EGFR-mediated activation of Akt/c-FLIP/COX-2 to support cell survival, thereby protecting cancer cells from damage caused by anticancer agents." (PMID 35006436, 2020). "This study provided a novel opportunity to document treatment patterns, use of EGFR mutation testing, and how patients with metastatic NSCLC are managed in a real-world clinical setting based on data from EHR used by US-based cancer care providers." (PMID 32345265, 2020). "The crosstalk between EGFR and other growth factor receptors markedly enhances the progression of cancer by the transactivation of EGFR through interaction with platelet-derived growth factor (PDGFR) and IGF-1R." (PMID 32708604, 2020). "Increased HB-EGF level in supernatants and decreased MICA level on cancer cells surface activated the EGFR pathway and induces immune escape, respectively." (PMID 32637415, 2020).
cancer (continued). "Herein, we report four platinum(II) terpyridine complexes bearing EGFR inhibiting 4-anilinoquinazoline derivatives as potent multi-targeting antiproliferation agents against a series of cancer cells." (PMID 32411653, 2020). "Lastly, we show that an IGFBP-3 Fc construct in combination with EGFR targeted therapy augments inhibition of cancer cells both in vitro and in vivo." (PMID 32066763, 2020). "QDs demonstrate results of molecularly directed images, as well as better quantitative detection of cancer molecules like Ki67 and EGFR, expressed on TNBC." (PMID 32245065, 2020). "Gefitinib is a small-molecule inhibitor of epidermal growth factor receptor (EGFR) tyrosine kinase used for certain breast, lung, and other cancers with mutated and overactive EGFR." (PMID 32322202, 2020). "Here, we examined the possibility of using internalizable anti-EGFR affibody as an EGFR-targeting MNT module for drug transport into the cancer cell nuclei." (PMID 32194412, 2020). "Our study suggests that EGFR plays an important role in the development of cancer stem cells by stabilizing SOX2." (PMID 31823521, 2020). "DNA JB4 inhibits Src phosphorylation by direct binding to the SH3 domain of c-Src and suppresses invasion of cancer by disrupting the interaction between Src and Src-downstream targets such as EGFR, FAK, and STAT3." (PMID 31952344, 2020). "Small molecule inhibitors or monoclonal antibodies blocking Abl, ErbB2, or EGFR have become the standard of care for these cancers." (PMID 32069833, 2020). "EGFR is a transmembrane receptor tyrosine kinase that controls cancer cell proliferation, migration, differentiation, and homeostasis." (PMID 33321953, 2020). "Activation of EGFR induces the proliferation and growth of cancer cells, and thus, provides a therapeutic target in advanced NSCLC." (PMID 32093010, 2020). "We investigated EGFR status via laser microdissection to capture spatially separated cancer cell subpopulations and digital droplet PCR to determine the abundance of EGFR sensitizing mutation and naïve T790M." (PMID 32093629, 2020). "Typically, the TF-induced EGFR activation is closely correlated with the procoagulant activity of cancer cells, which is achieved through the Nuclear transcription factor activates protein-1 (AP-1) transcriptional activation." (PMID 33243184, 2020). "HBEGF, a ligand for EGFR (Epidermal Growth Factor Receptor), was shown to increase invasiveness of cancer cells to the brain." (PMID 32645833, 2020). "Recently, the activation of a signal transducer and activator of transcription 3 (STAT3) has been described as an alternative resistance mechanism allowing cancer cells to escape the EGFR signaling or the TKI suppression." (PMID 32438613, 2020). "Inhibition of ferroptosis is potential to facilitate sorafenib (an EGFR inhibitor) resistance to cancer cells." (PMID 33425751, 2020). "The overexpression and/or hyperactivation of Src have been reported in human cancers and lead to the upregulation of various receptors of tyrosine kinases (RTKs), including EGFR, HER2, c-MET, PDGFR, IGFR, FGFR, and VEGFR." (PMID 32466572, 2020). "Further, our analysis show that multiple survival mechanisms act in concert to reduce the effect of EGFR inhibition, which poses the question of how many drugs we need to combine in order to kill the cancer cells." (PMID 32234966, 2020). "The discovery of EGFR-activating mutations in NSCLC and the successful use of EGFR-TKIs have shifted the focus of cancer treatment from empirical cytotoxic chemotherapy to molecularly targeted therapies." (PMID 33276757, 2020). "Several quinazolines have been evaluated as anticancer therapeutics in different cancer cell lines and EGFR has been identified as one of the relevant molecular targets." (PMID 32974274, 2020).
cancer (continued). "At the transcription level, RNA expressions of the EGFR gene in HPV-negative cancers were 1.619 times (95% CI 1.22 to 2.14) higher than HPV-positive cancers in the overall head and neck cohort (p < 0.0001)." (PMID 32775042, 2020). "It has been known that lapatinib has its anti-cancer activity through inhibition of epidermal growth factor receptor (EGFR) and human epidermal growth factor receptor 2 (HER2)." (PMID 32576928, 2020). "The evidence that c-Src over-expression is reported in ~50 to 80% of NSCLC patients led to increased research efforts for investigating the effects of concurrent c-Src/EGFR inhibition on cancer growth and dissemination." (PMID 32517369, 2020). "In preclinical models, AZD8931 has greater anti-cancer activity than other EGFR inhibitors, such as gefitinib and lapatinib, which have narrower spectrums of erbB receptor inhibition." (PMID 31765988, 2020). "EGFR, also known as HER1 and ErbB1, has received much attention as a marker, growth driver, and therapeutic target for cancers." (PMID 32194412, 2020). "The therapeutic importance of such compounds has been demonstrated by the progression of HDAC/kinase dual inhibitors into clinical trials for cancer treatment —CUDC-101 (HDAC/EGFR inhibitor) and CUDC-907 (HDAC/PI3K inhibitor)." (PMID 32987782, 2020). "Palmitoylation has been found to regulate many cancer-related proteins such as Ras, Wnt, Shh, and epidermal growth factor receptor (EGFR)." (PMID 32377193, 2020). "The scaffolding protein EBP50 also is involved in the pathogenesis of cancer by interacting with EGFR and PDGFRβ with its PDZ domains." (PMID 32708604, 2020). "Further, the activation of the EGFR oncogene pathway induces the release of several immunosuppressive factors to accomplish evasion of the host anti-cancer immune response." (PMID 32760402, 2020). "When the EGFR path is blocked by Erlotinib, the cancer cells have to develop another oncogenic path for their continuous survival." (PMID 33194732, 2020). "About 60–80% of these cancers express variable levels of the epidermal growth factor receptor (EGFR), which for many years was considered to be a major oncogene and a promising therapeutic target in these tumors." (PMID 32784650, 2020). "While EGFR can bind up to twelve distinct ligands, cancer targeting has been attempted mainly with two ligands, EGF and TGF-alpha." (PMID 32957689, 2020). "For instance, in cancer cells, coactivation of Axl with EGFR or CUB domain–containing protein-1 (CDCP1) has been shown to enhance cancer cell survival and their invasiveness." (PMID 32970632, 2020). "The ERK1/2 pathway is primarily driven by EGFR in vitro and in vivo in various types of cancers and is a potential target in cancer therapy." (PMID 32051269, 2020). "It had considerable “protective” anti-cancer properties and concomitantly down regulated EGFR, HER-2 and PTGS-2 (COX-2), while having significant anti-CRC effects on CRC mice models." (PMID 32401801, 2020). "Accordingly, depletion of USP18 activates miR–7 and subsequently downregulates the expression of EGFR, thereby leading to the suppression of tumorigenesis and the facilitation of apoptosis of cancer cells." (PMID 32957626, 2020). "Anti-EGFR antibodies are known to induce cancer cell death via apoptosis; we, therefore, investigated the expression of apoptotic signals in CRC cells treated with Cet or Pab." (PMID 32703218, 2020).
cancer (continued). "One important mechanism whereby cancer cells achieve increased and uncontrolled EGFR signaling is escaping down-modulation of the receptor." (PMID 33202887, 2020). "Some inhibitors of EGFR, including small tyrosine kinase inhibitors and monoclonal antibodies, are currently applied in the clinic for cancer treatment, such as non-small cell lung cancer." (PMID 31937753, 2020). "ECM composition is altered dynamically during cancer progression, making the regulation of EGFR signaling by matrix proteins in cancers of direct interest." (PMID 32719793, 2020). "In conclusion, results of this study demonstrate that XLEP can suppress the proliferation and autophagy of EGFR-TKI-resistant cancer cells to solve the problem that EGFR-TKI-resistant cancer cells is insensitive to gefitinib." (PMID 32256661, 2020). "Meanwhile, several natural compounds which is aboundant in the nature have also been found to inhibit EGFR, mainly via effects on downstream signaling pathway in different cancer models." (PMID 33292235, 2020). "It has been reported that EGFR inhibitors exhibit prominent anti-angiogenesis and anti-cancer activities." (PMID 31892990, 2020). "Above all, FGFR-TKIs show the potential for application in the treatment of EGFR-TKI-resistant cancer cells." (PMID 33092268, 2020). "A431 cells, which are considered model EGFR-overexpressing cancer cells, were treated with TiO2 PEG NPs and EGF-TiO2 PEG NPs, then the localization of EGFR was visualized by immunofluorescence staining." (PMID 33003324, 2020). "Unfortunately, EMab-17 was not suitable for Western blot and immunohistochemical analyses (data not shown); therefore, EMab-51 or EMab-134 should be used for diagnosing EGFR expression in cancer patients." (PMID 32218834, 2020). "Epidermal growth factor receptor plays an important role in mediating cell proliferation, apoptosis, angiogenesis, and other cancer progression‐related functions." (PMID 32592435, 2020). "This multi-dimensional role of EGFR in the progression and aggressiveness of cancer, has evolved from conventional to more targeted therapeutic approaches." (PMID 33014289, 2020). "Human epidermal growth factor receptor (ErbB) family has been the first receptor family discovered as involved in human cancers." (PMID 33028922, 2020). "Epidermal growth factor receptor (EGFR) is a pro-tumorigenic receptor tyrosine kinase that facilitates growth for cancer cells that overexpress the receptor." (PMID 32069320, 2020). "One group represented traditional signal pathways, including the pathways involved in cancer, EGFR tyrosine kinase inhibitor pathways, PI3K-Akt signaling pathways, and Ras signaling pathways." (PMID 33335254, 2020). "EGFR served as the biological marker because it is highly overexpressed in SCC as well as in other human cancers." (PMID 31963462, 2020). "KIAA1199 promotes cancer cell proliferation and migration by regulating EGFR‐mediated signaling pathways." (PMID 32519472, 2020). "Some of the reported mechanisms underlying the acquired resistance to crizotinib in ALK translocated cancers involve secondary mutations, ALK amplification, KIT amplification, and autophosphorylation of epidermal growth factor receptor (EGFR)." (PMID 32133282, 2020). "(2018a) who engineered anti-CD3 and anti-EGFR on the surface of the exosomes allowing a cross-link of T cells and EGFR + cancer cells and eliciting potent antitumor immunity." (PMID 32264719, 2020). "In our meta-analysis, we observed a significantly worse OS and PFS in patients receiving GAS during cancer treatment with anti-EGFR TKIs or capecitabine-based regimens in GI cancers and NSCLC." (PMID 32325628, 2020). "The encouraging preclinical data pushed forward testing the combination of EGFR and c-Src inhibitors in clinical trials, particularly in cancer patients who progressed after EGFR inhibitors." (PMID 32517369, 2020).
cancer (continued). "Previous studies indicated that ADAM9 activated EGFR-AKT pathway via shedding HB-EGF from cell surface to promote cancer progression." (PMID 32637415, 2020). "Prolonged EGFR-inhibition treatment in cancer cells sensitive to EGFR inhibition led to increased complement activation." (PMID 32054454, 2020). "Many developmental pathways (including NOTCH, Wnt/β-Catenin, Sonic Hedgehog, EGFR/PI3K/Akt/mTOR pathways) that maintain the self-renewal property of cancer stem-like cells have been identified." (PMID 35692625, 2020). "Significant research efforts have sought to gain deeper information of the EGFR signaling and EGFR-mediated fatal oncology in human cancer." (PMID 32321917, 2020). "Increasingly, studies have revealed the important role of PAK1-regulated EGFR/HER2/MAPK pathways in cancer." (PMID 32863957, 2020). "Among the proteins interacting with FDFT1, those related to cancer metabolism include EGFR, FN1, sodium-taurocholate co-transporting polypeptide (SLC10A1), and WWOX." (PMID 33113804, 2020). "EGF/EGFR signaling is dysregulated in many cancers including: breast, gastric, HCC, lung and ovarian." (PMID 32018226, 2020). "Among patients with EGFR-mutant cancer, the EI-L-type group had poorer prognosis than the EI-H-type group." (PMID 32277151, 2020). "The bispecific antibody targeting both IGF-IR and EGFR holds promise in treating cancer, since it inhibits tumor growth and metastasis in preclinical studies." (PMID 32493414, 2020). "Like in many other cancers, we can find that the epidermal growth factor receptor (EGFR), a tyrosine kinase, or its ligands is overexpressed in SCC." (PMID 31963462, 2020). "The network revealed that CRC-related DERs such as hsa-miR-1-3p, hsa-miR-490-3p, hsa-miR-542-5p, hsa-miR-424-5p, and hsa-miR-133a-3p are associated with the regulation of several cancer-related pathways by targeting TIMP3, FOS, PPP1R12B, CCND2, and EGFR." (PMID 32153636, 2020). "Double-stranded miR-16 was delivered by non-living bacterial minicells with a targeting moiety (i.e., an anti-EGFR bispecific antibody that recognizes EGFR-expressing cancer cells)." (PMID 32906681, 2020). "HBEGF is a ligand for EGFR that was shown to increase migration and invasiveness of cancer cells and was identified specifically in brain metastasis compared to the bone and lung." (PMID 32645833, 2020). "EGFR normally activates relevant genes, resulting in cell division and proliferation, although its overexpression has been observed in some forms of cancer." (PMID 34567646, 2020). "Recent case reports have suggested that EGFR inhibitors markedly reduced neuropathic pain in cancer patients." (PMID 32111605, 2020). "The most enriched pathways of these DEGs are cancer-related signaling pathways such as ErbB-epidermal growth factor receptor (EGFR) and mitogen-activated protein kinase (MAPK) signaling pathways." (PMID 33202602, 2020). "Aberrant activation of the epidermal growth factor receptor (EGFR) is involved in the pathogenesis and progression of several human cancers, including NSCLC." (PMID 32676036, 2020). "This leads to the acceleration of α5β1 integrin and EGFR recycling, elevated Akt activation, and a concomitant increase in the random migration of cancer cells." (PMID 32842549, 2020). "The acquired resistance to anti-EGFR antibodies emerged at least in part by the selection of cancer cell subpopulations with increased angiogenic potential, as a 5–10-fold increase in the expression of VEGF was observed." (PMID 32704062, 2020). "Profiling of the allosteric SHP2 inhibitor SHP099 across cancer cell lines harboring various RTK dependencies reveals that FGFR-dependent cells are often insensitive to SHP099 when compared to EGFR-dependent cells." (PMID 32076487, 2020). "We demonstrated that limited c-Cbl availability determines the uncoupling of EGFR phosphorylation and ubiquitylation at the supraphysiological EGFR level occurring in cancer." (PMID 33202887, 2020).